XIAP (X-linked inhibitor of apoptosis)
Diseases named in the same sentence as XIAP in open-access papers (continued):
Sharing a sentence is not in itself a finding about the gene and the disease.
ovarian carcinoma (continued). "Modulating XIAP expression using RNAi enabled caspase 3 activation and the apoptosis of ovarian cancer cells treated with docetaxel." (PMID 36551731, 2022). "Triptolide promotes intracellular accumulation of ROS to inhibit NF-κB signaling and down-regulate Bcl-2 and X-linked inhibitor of apoptosis protein (XIAP) as anti-apoptotic factors, increasing CP sensitivity of ovarian cancer cells." (PMID 33921908, 2021). "Firstly, we found that the expression of GLT8D2, FRS2a (Tyr196), AKT (Ser473) and XIAP were significantly increase in six platinum resistant clinical ovarian cancer samples, compared with six platinum sensitive clinical ovarian cancer samples." (PMID 34294681, 2021). "The results obtained from several studies suggest that ectopic expression of miR-137 and miR-149 can suppress the XIAP 3′UTR function and decrease the levels of XIAP protein in ovarian cancer cells." (PMID 34721577, 2021). "Cisplatin induces XIAP content decrease and cytosolic HtrA2/Omi level increase in cisplatin-sensitive ovarian cancer cells." (PMID 35582023, 2021). "It is believed that XIAP participates in raising cellular resistance to chemotherapy in ovarian cancer, since miR-519d and miR-149 sensitized ovarian cancers to cisplatin-induced cytotoxicity by suppressing XIAP." (PMID 33138314, 2020). "In ovarian cancer, miRNA-142 has been shown to sensitise cell lines to cisplatin by repressing XIAP, a mediator of chemoresistance in this tumor type, and other apoptotic regulators." (PMID 31979312, 2020). "For instance, while the anti-apoptotic proteins survivin and XIAP confer anoikis resistance in ovarian cancer, the related molecule CIAP-1 plays this role in PDA." (PMID 32780245, 2020). "Specific siRNA, targeting XIAP, promoted apoptosis and enhanced cellular sensitivity to paclitaxel in ovarian cancer environment." (PMID 33138314, 2020). "c-IAP1 and XIAP (X-linked IAP) overexpression is associated with chemoresistance and as a biomarker for ovarian cancer." (PMID 33182737, 2020). "Many micro RNAs, such as miR-137, influenced the mRNA stability of XIAP by binding to its 3′-UTR in ovarian cancer." (PMID 33138314, 2020). "miR-137 can regulate XIAP via its 3′UTR sensitise ovarian cancer cells to cisplatin-induced apoptosis in ovarian cancer." (PMID 30866999, 2019). "Various reports have emerged claiming that IAPs are deregulated in ovarian cancer cells and XIAP are involved in ovarian cancer chemoresistance." (PMID 31766284, 2019). "Therefore, we may conclude that CK1δ knockdown is functionally associated with p21(Cip1/Waf1) and XIAP downregulation, and this could be a possible explanation for ovarian cancer cell sensitization to CPT treatment, probably due to an impaired DNA-damage response and apoptosis control." (PMID 31799185, 2019). "Recently, XIAP has been reported in the PTX-induced TLR4/MyD88-dependent signaling pathway in ovarian cancer." (PMID 29486738, 2018). "APG-1387 induced ovarian cancer cell death via decreasing expression of cIAP1, cIAP2, XIAP in a dose- and time-dependent manner." (PMID 29530056, 2018). "In ovarian cancer cells, cisplatin-induced DNA damage results in activation of AKT and phosphorylation of X-linked inhibitor of apoptosis (XIAP)." (PMID 28572758, 2017). "In addition to anti-apoptotic Bcl-2 family proteins, XIAP (X-linked inhibitor of apoptosis protein) may be a key determinant in chemosensitivity by suppressing the apoptotic activities induced by cisplatin in ovarian cancer." (PMID 27935869, 2017). "Recent reports demonstrated that multiple miRNAs through their down-regulation function can regulate XIAP in ovarian cancer cells, thus enhancing our understanding of the function and regulation of XIAP." (PMID 28186968, 2017). "Recently, miR-509-3p was confirmed to directly target XIAP and inhibit proliferation and increase sensitivity to cisplatin in chemoresistant ovarian cancer cells." (PMID 27036018, 2016).
ovarian carcinoma (continued). "AKT, which is strongly activated by oncogenic KIT, was found to stabilize XIAP in AKT-transfected human ovarian cancer epithelial cell line A2780S and human embryonic kidney (HEK) 293 cells." (PMID 27167336, 2016). "Activation of the PI3K/protein kinase B (Akt) pathway leads to the upregulated expression of XIAP, which modulates death signaling pathways and is a determinant of cisplatin resistance in ovarian cancer cells." (PMID 23817665, 2013). "Akt phosphorylation of XIAP led to increased stability and decreased cell apoptosis in ovarian cancer treated with cisplatin." (PMID 23922886, 2013). "Previous studies have shown that acquired cisplatin resistance in ovarian cancer is correlated with an increased expression of Bcl-2 and XIAP, which are regulated by NF-κB." (PMID 24137468, 2013). "β-Elemene not only reduced the XIAP protein level but also abrogated cisplatin-induced XIAP expression in resistant ovarian tumor cells, indicating the involvement of XIAP in the mechanism of β-elemene action in resistant ovarian cancer cells." (PMID 23817665, 2013). "The results are consistent with previous reports showing that the down-regulation of XIAP sensitizes cancer cells to therapeutic drugs in lung cancer, prostate cancer, ovarian cancer and pancreatic cancer." (PMID 22403616, 2012). "A previous study reported that XIAP is phosphorylated by AKT on Ser87 which leads to increased stabilization of XIAP and decreased apoptosis of ovarian cancer cells in response to cisplatin." (PMID 21559296, 2011). "Increased XIAP has been reported in a variety of human tumors, including oesophageal carcinoma, clear cell renal carcinoma, ovarian carcinoma, and lymphoma." (PMID 19397802, 2009). "Our study identifies a potential inverse correlation between MLH1 expression and XIAP anti-apoptotic activity in chemotherapy response in ovarian cancer cells." (PMID 19603033, 2009). "Cisplatin sensitivity in ovarian cancer has been correlated with inhibition of XIAP, consistent with the observations in this study." (PMID 19603033, 2009). "In ovarian cancer we showed that both knock down of XIAP by RNA interference and pretreatment with Phenoxodiol result in similar sensitization to chemotherapy." (PMID 17257402, 2007). "(II) Activating cell survival pathway to suppress apoptosis: Ovarian carcinoma-TA-MSCs protect cancer cells from carboplatin-induced apoptosis through activating PI3K-AKT pathway and phosphorylation of X-linked inhibitor of apoptosis protein (XIAP)." (PMID 40676710, 2025). "This was evident based on the relatively high basal level of phosphorylated AKT in the untreated TOV21G cells, which is consistent with our other findings regarding these specific ovarian cancer cells expressing high amount of anti-apoptotic proteins (Mcl-1, XIAP, and Bcl-xL)." (PMID 39334906, 2024). "According to reports, XIAP is upregulated in epithelial ovarian cancer, and this upregulation of XIAP may play a role in the emergence and development of ovarian cancer." (PMID 37222810, 2023). "A study reported that Akt phosphorylation could inhibit XIAP ubiquitination, reduce its degradation, and partially reverse cisplatin-induced apoptosis of ovarian cancer epithelial cells, indicating that XIAP can be an Akt substrate." (PMID 35446864, 2022). "As such, down-modulation of XIAP activity has been studied as a mechanism to increase apoptosis and to overcome continued cell proliferation in vitro and in preclinical mouse models of ovarian cancer." (PMID 35279106, 2022). "In addition, ATM regulates PTEN, the antagonist of PI3K through p85α and XIAP mediated proteasome degradation in ovarian cancer cells (OVCAR3, OVCAR4) and human epithelial ovarian tumors." (PMID 33802884, 2021). "XIAP plays a crucial role in chemotherapy resistance in ovarian cancer and various tumors." (PMID 34721577, 2021). "Similarly, it is indicated that miR‐130a targets XIAP so as to regulate cisplatin chemosensitivity in the cells ovarian cancer." (PMID 32790238, 2020).
ovarian carcinoma (continued). "Clinical significance of ATM, PTEN, p85α, and XIAP expression in human ovarian cancers: Similar to the data shown for LN18 cells, ATM depletion in p85α deficient OVCAR3 cells was associated with reduced migration and invasion compared to p85α proficient OVCAR4 cells." (PMID 31635307, 2019). "Thus, the inhibition of XIAP is a mechanism leading to increased apoptosis in platinum-resistant ovarian cancer cells in vitro and in vivo." (PMID 31766284, 2019). "Chemoresistant ovarian cancer cells not only upregulated multidrug resistant-associated proteins (MDR1 and MRP1-3) but also induced the expression of anti-apoptotic proteins, including X-linked inhibitor of apoptosis protein (XIAP), and cell survival." (PMID 31336860, 2019). "Furthermore increased XIAP levels have also been reported for ovarian carcinoma, B-cell Non-Hodgkin and Hodgkin lymphoma, clear cell renal cancer, esophageal carcinoma, and non-small cell lung cancer." (PMID 25120954, 2014). "Down-regulation of XIAP expression in ovarian cancer cells results in apoptosis in vitro and prolonged survival of ovarian cancer-bearing mice, which indicate that XIAP may be a valuable therapeutic target in ovarian cancers." (PMID 20184758, 2010). "HNTMB may be an alternative apoptosis inducing drug in certain platinum-resistant cancers via XIAP reduction as shown to occur in SKOV-3 ovarian cancer cells used in the present study." (PMID 20184758, 2010). "The X-linked inhibitor of apoptosis protein (XIAP), an endogenous apoptosis suppressor, can determine the level of caspase accumulation and the resultant response to apoptosis-inducing agents such as cisplatin in epithelial ovarian cancer (EOC)." (PMID 19603033, 2009). "Further studies testing various dosing regimens are necessary to evaluate whether any potential synergy exists between cisplatin and XIAP inhibition in MLH1-proficient ovarian cancer cells." (PMID 19603033, 2009). "Furthermore, we showed that pretreatment of chemotherapy-resistant ovarian cancer cells with Phenoxodiol results in decreases in XIAP levels and sensitization to Gemcitabine, Carboplatin and Paclitaxel." (PMID 17257402, 2007). "Our data suggest that HOXB9 overexpression may cause chemoresistance in ovarian cancer cells by differential induction of ERCC-1, MRP-2, and XIAP depending on the strength of HOXB9 expression through inhibition of the mitochondrial pathway of apoptosis, including Bax/Bcl-2." (PMID 36674764, 2023). "We demonstrated that platinum resistance, which is mediated by cisplatin-induced ERCC-1, MRP-2, and XIAP in SKOV3 ovarian cancer cells (with a moderate level of HOXB9 expression), could be overcome by cisplatin treatment alone through the inhibition of Bcl-2 and activation of Bax." (PMID 36674764, 2023). "Furthermore, miR-107 could regulate the XIAP/caspase-3 signaling pathway in ovarian cancer by targeting SMAC." (PMID 35281523, 2022). "Furthermore, we found miR-107 could regulate the XIAP/caspase-3 signaling pathway in ovarian cancer by targeting SMAC." (PMID 35281523, 2022). "Previous evidence indicates that the RING-domain E3 ubiquitin ligases including Cullin-RING E3 ligase complexes such as SCF complex (SKP1, Cullin and F-box protein), the APC/C complex, as well as monomeric XIAP, MDM2, MUL-1, Pirh2, and SIAH2 may all be associated with ovarian cancer chemoresistance." (PMID 35582023, 2021). "In epithelial ovarian cancer, miR-509-3p could immediately target XIAP by its 3¢-UTR." (PMID 32519740, 2020). "Hence, we speculated that the miR-141-induced anoikis resistance is mediated through suppression of KLF12, which, in turn, upregulates survivin and XIAP expression to inhibit ovarian cancer cell apoptosis." (PMID 28095864, 2017).
ovarian carcinoma (continued). "LINC-DUBR suppressed malignant progression of ovarian cancer by downregulating miR-107 to induce SMAC expression and involving in the XIAP/caspase-3 signaling pathway." (PMID 35281523, 2022). "In conclusion, LINC-DUBR suppressed the malignant progression of ovarian cancer by downregulating miR-107 to induce SMAC expression and involving in the XIAP/caspase-3 signaling pathway." (PMID 35281523, 2022). "We previously established that COL11A1 promotes cisplatin resistance in ovarian cancer cells through activation of NFkB and upregulation of specific inhibitors of apoptosis (IAPs; BIRC2, BIRC3, and XIAP)." (PMID 34638339, 2021). "The correlation of GLT8D2 expression and XIAP, an important anti-apoptosis factor and downstream molecules of PI3K/AKT signalling, was further confirmed in clinical ovarian cancer samples with chemotherapy (r = 0.77, P < 0.05)." (PMID 34294681, 2021). "In ovarian cancer patients, ATM, PTEN, p85α, and XIAP protein levels predicted better progression free survival after platinum therapy." (PMID 31635307, 2019). "DEBIO-1143 promoted XIAP degradation and initiated poly-ADP ribose polymerase (PARP)-dependent apoptotic pathway displaying single-agent activity against ovarian cancer cells." (PMID 31766284, 2019). "We then conducted immunohistochemical investigations of ATM, XIAP, PTEN, and p85α in a large clinical cohort of 525 human epithelial ovarian cancers treated at Nottingham University Hospitals (NUH) between 1997 and 2010." (PMID 31635307, 2019). "In clinical cohorts of human ovarian cancers, we have demonstrated ATM, PTEN, p85α and XIAP expression as predictors of response to platinum chemotherapy." (PMID 31635307, 2019). "In-depth analysis of BCL-2 family proteins and other apoptotic regulators in response to PI3K/mTOR pathway blockade identifies BIM, caspase-3, BCL-XL, XIAP, and MCL-1 as critical players in ovarian cancer cell survival." (PMID 28848242, 2017). "XIAP is suggested as a activator in PI3K/AKT survival pathway in chemo-sensitive and chemo-resistant ovarian cancer cell lines." (PMID 27935869, 2017). "The effect of DIG-MSK was also evident on the loading of Sp1 on the other gene promoters: XIAP whose down-regulation can induce cell death, CRABP1, a gene involved in the development of ovarian carcinoma, and MDK that is a marker in ovarian cancer." (PMID 25110883, 2014). "Additionally, the degradation of the X-linked inhibitor of apoptosis protein (XIAP) by HtrA1 plays a role in the cellular response to chemotherapy, suggesting that restoring HtrA1 expression could be a promising therapeutic approach for treating ovarian cancer." (PMID 38793064, 2024). "miR-509-3p directly targets XIAP to inhibit proliferation, and targets XIAP, Golgi phosphoprotein-3 (GOLPH3), and Wnt ligand secretion mediator (WLS) to regulate platinum sensitivity in chemoresistant ovarian cancer cells." (PMID 37386587, 2023). "In order to most effectively target ovarian cancer cells and decrease systemic toxicities, the delivery of the XIAP antagonist has been rendered cancer selective by linking the SMAC mimetic to the sigma-2 ligand SW43, the receptors of which are upregulated in ovarian cancer cells." (PMID 35279106, 2022). "It has previously been reported that cisplatin down-regulates XIAP in chemosensitive ovarian cancer cells, whereas chemoresistant cells are not affected." (PMID 35582023, 2021). "Western blot analyses indicated that Sp1 could significantly elevate the expression levels of survivin as well as XIAP, while KLF12 had the opposite effects compared to Sp1 and suppressed survivin and XIAP expressions in both ovarian cancer cell lines." (PMID 28095864, 2017).
ovarian carcinoma (continued). "In one study, cisplatin decreases the XIAP content in cisplatin-sensitive, but not cisplatin-resistant, human ovarian cancer cells." (PMID 23817665, 2013). "XIAP and cIAP are the most prominent and potent members of this family and its pharmacologic blockade with SMAC mimetics has been shown in a number of experimental settings but also as a means to sensitize ovarian cancer efficiently to chemotherapy, including in a clinical setting." (PMID 35279106, 2022). "Furthermore, using a Human Apoptosis Array Kit consisting of 35 apoptosis-related proteins (R&D) with either miR-141-overexpressing or KLF12 knockdown ovarian cancer cells, 8 out of 35 proteins (HO-2/HMOX2, ph-Rad 17, CIAP-2, survivin, HSP-70, TNFR1/TNFRSF1A, clusterin and XIAP) were upregulated." (PMID 28095864, 2017). "In addition, MLH1 proteolysis increased active forms of caspase-3 and -9, and decreased cell viability was observed when XIAP was specifically inhibited using a siRNA in the MLH1-proficient and not in the MLH1-deficient ovarian cancer cells." (PMID 19603033, 2009). "In conclusion, the platinum resistance of SKOV3 ovarian cancer cells may be different in terms of its refractoriness to cisplatin treatment according to the level of HOXB9 overexpression and the subsequently induced expression of ERCC-1, MRP-2, and XIAP, as well as Bcl-2/Bax expression." (PMID 36674764, 2023). "Similarly, increased expression of the inhibitor of apoptosis BIRC4 (XIAP) could also contribute to oxaliplatin resistance and counteract the increased expression of the cell death execution caspases 6 and 7 in the platinum-resistant ovarian cancer cell lines." (PMID 31344863, 2019).